MIR4535 (microRNA 4535)
Synonyms: hsa-mir-4535
Gene: MicroRNA gene on chromosome 22 (48,780,295 to 48,780,353, forward strand). Ensembl gene ENSG00000266887.
Homologues: Orthologues: chimpanzee MIR4535 (100% identical).